LEAP2 (liver enriched antimicrobial peptide 2)
Diseases named in the same sentence as LEAP2 in open-access papers (continued):
Sharing a sentence is not in itself a finding about the gene and the disease.
type 1 diabetes mellitus (3 papers, 2022 to 2025). A chronic condition characterized by minimal or absent production of insulin by the pancreas. "In addition, the levels of LEAP2 in plasma were higher in type 1 diabetic mice during CR; and the blood glucose levels were reduced by over-expression of LEAP2 in mice." (PMID 35521798, 2022).
anorexia nervosa (2 papers, 2023 to 2026). A disorder most often seen in adolescent females characterized by a refusal to maintain a minimally normal body weight, an intense fear of gaining weight, a disturbance in body image, and, in postmenarcheal females, the development of amenorrhea. "Recents findings suggest that the ghrelin/LEAP2 (Liver Expressed Antimicrobial Peptide 2) ratio impacts the dynamics of reward sensitivity, and that LEAP2 may serve as a biomarker of remission in patients with anorexia nervosa (AN)." (PMID 41786704, 2026). "This study investigates the evolution of plasma ghrelin and LEAP-2 concentrations in 29 patients with anorexia nervosa (AN) before and after refeeding and compares it to physiological adaptations during fasting in healthy controls or to mouse model of chronic food restriction and refeeding." (PMID 37867951, 2023).
Cachexia (2 papers, 2025). Severe weight loss, wasting of muscle, loss of appetite, and general debility related to a chronic disease. "Ghrelin resistance in cachexia can be treated by blocking LEAP2 action to enhance ghrelin signaling through LEAP2/ghrelin ratio modulation." (PMID 40869331, 2025).
cognitive decline (2 papers, 2023 to 2024). "Whether this age-related upward shift in the LEAP2/ghrelin balance occurs as a natural defense against potentially deleterious, age-associated metabolic changes — perhaps at the expense of cognitive decline — is an interesting thought experiment." (PMID 37212281, 2023). "In this study, we have identified an unprecedented role of disrupted LEAP2/ghrelin balance in the development of hippocampal synaptic deficits and cognitive decline during aging." (PMID 37212281, 2023). "To establish a direct link between LEAP2 dysregulation and age-related cognitive decline, we employed lentiviral shRNA silencing of Leap2 to downregulate LEAP2 production in aged mice." (PMID 37212281, 2023). "Given the direct deleterious impact of LEAP2 dysregulation on ghrelin’s function in promoting hippocampal fitness, modulation of the LEAP2/ghrelin balance, therefore, holds promise to rejuvenize cognitive functions or, at very the least, to delay cognitive decline in aging." (PMID 37212281, 2023). "Therefore, the age-related changes of LEAP2 may precipitate cognitive decline and function as an indicator of memory disturbances during aging." (PMID 37212281, 2023).
cognitive deficits (2 papers, 2023 to 2024). "In our future study, we will recruit a larger cohort with a wider range of BMI and itemized MMSE scores to evaluate the diagnostic capacity of LEAP2/ghrelin imbalance in identifying hippocampus-related cognitive deficits during normal aging." (PMID 37212281, 2023). "Our results suggest that LEAP2 elevation accompanies aging and further imply that the imbalanced plasma LEAP2/ghrelin levels are related to the development of cognitive deficits with advanced age." (PMID 37212281, 2023). "The elevated LEAP2/ghrelin molar ratio accompanying aging blunted hippocampal ghrelin signaling, resulting in suppressed hippocampal synaptic function, impaired hippocampal neurogenesis, and neuroinflammatory damage, culminating in cognitive deficits." (PMID 37212281, 2023). "LEAP2/ghrelin imbalance is associated with cognitive impairment in elderly participants without dementia." (PMID 37212281, 2023).
depression (2 papers, 2022 to 2025). "Third, we did not measure other circulating peptides, such as leptin, which has been linked to depression or LEAP-2, an antagonist of ghrelin which can influence the activity of ghrelin." (PMID 39905823, 2025).
hyperlipidemia (2 papers, 2023 to 2025). "Recently, it was reported that knockdown of LEAP-2 ameliorated HFD-induced hyperlipidemia, inflammation, and myocardial injury." (PMID 41303478, 2025). "It has been shown that knockdown of LEAP-2 relieved hyperlipidemia, inflammation, and myocardial injury in obese mice by polarizing macrophages toward the M2 phenotype." (PMID 41303478, 2025).
Alzheimer’s dementia (1 paper, 2023). "Another critical issue that merits discussion is whether LEAP2 dysregulation is mechanistically associated with increased risk of Alzheimer’s dementia." (PMID 37212281, 2023).
bacteremia (1 paper, 2021). "In this study, the CSF‐to‐serum ratio of LEAP2 in the patient with Listeria meningitis was markedly higher than that in the patient with bacteremia (0.532 versus." (PMID 33811478, 2021). "The patient with bacteremia had a normal CSF LEAP2 concentration but an elevated serum LEAP2 concentration, while the reverse was true in the patient with Listeria meningitis." (PMID 33811478, 2021). "The serum LEAP2 concentration in the patient with Listeria meningitis (13.47 ng/ml) was also within this range, while that in the patient with bacteremia (31.40 ng/ml), who had no CNS infection, was higher than the range observed in the healthy subjects." (PMID 33811478, 2021).
Cirrhosis (1 paper, 2024). A chronic disorder of the liver in which liver tissue becomes scarred and is partially replaced by regenerative nodules and fibrotic tissue resulting in loss of liver function. "We suggested expanding the sample size and conducting patient follow-up to investigate further the relationship between LEAP-2 levels and liver fibrosis, and cirrhosis, and exclude the influence of alcohol factors." (PMID 38778244, 2024). "Secondly, we will study the expression levels of CK18 and LEAP-2 in MAFLD related liver fibrosis and cirrhosis to investigate the roles and possible mechanisms of these indicators in the occurrence and progression of MAFLD." (PMID 38778244, 2024).
coccidiosis (1 paper, 2021). A parasitic infection caused by Coccidia. "Another study observed LEAP2 transcription during Eimeria infection in a supposedly coccidiosis-resistant Fayoumi chicken line similar to noninfected levels of transcription." (PMID 33652244, 2021).
dementia (1 paper, 2023). Loss of intellectual abilities interfering with an individual's social and occupational functions. "Here, we show an age-related elevation in circulating LEAP2 alongside a marginal decrease in ghrelin, resulting in an increased LEAP2/ghrelin molar ratio in a cohort of elderly participants without dementia." (PMID 37212281, 2023). "In view of the importance of ghrelin signaling to cognition, we examined the potential impact of the age-related LEAP2/ghrelin imbalance on cognition in our cohort of elderly participants without dementia." (PMID 37212281, 2023). "LEAP2/ghrelin imbalance is an age-related change in elderly participants without dementia." (PMID 37212281, 2023).
E. coli infections (1 paper, 2023). "Moreover, the MIC of 2.78 μM for Ll-LEAP2 against S. enterica and E. coli was considered to be relatively low, suggesting that this peptide can potentially inhibit S. enterica and E. coli infections." (PMID 36765333, 2023).
hepatoma (1 paper, 2021). "In consistent with this, an in vitro study revealed that LEAP-2 expression was induced by high-cholesterol sera treatment in a human hepatoma cell line." (PMID 34512549, 2021). "LEAP-2 expression in a human hepatoma cell line was induced and reduced by high-cholesterol sera and polyunsaturated fatty acids (PUFAs) treatments, respectively." (PMID 34512549, 2021).
Hyperinsulinemia (1 paper, 2025). An increased concentration of insulin in the blood. "In our present study, endogenous hyperinsulinemia in patients with insulinoma was positively correlated with circulating LEAP2 levels, supporting Johansen’s finding." (PMID 41488138, 2025). "Serum LEAP2 levels are elevated in insulinoma and correlate with hyperinsulinemia and BMI." (PMID 41488138, 2025). "Given that hepatocytes commonly express insulin receptors, we hypothesize that endogenous hyperinsulinemia may partly drive hepatic secretion of LEAP2 in patients with insulinoma." (PMID 41488138, 2025). "Patients with hyperinsulinemia had significantly higher serum LEAP2 levels than those without hyperinsulinemia (median 24.6 ng/mL, range 9.95-79.1 ng/mL vs. 18.4 ng/mL, range 2.02-16.34 ng/mL; P = 0.021)." (PMID 41488138, 2025).
Hypoglycemia (1 paper, 2022). A decreased concentration of glucose in the blood. "In addition, continuous LEAP2 treatment of calorie-restricted GHSR-knockout mice could still induce body weight loss, hypoglycemia, and body temperature reduction, implying LEAP2’s ghrelin–GHSR signaling independent effects." (PMID 36387867, 2022).
insulinomas (1 paper, 2025). "LEAP2 expression was common in insulinomas, being detected in 23 of 26 cases (89%), compared with only 3 of 13 paired para-tumoral tissues (23%; P < 0.0001)." (PMID 41488138, 2025). "LEAP2 is expressed in insulinoma tissue, suggesting a potential role in the metabolic profile of these patients." (PMID 41488138, 2025). "LEAP2 expression was identified in 89% of insulinomas, and patients with a larger tumor burden tended to have higher serum LEAP2 levels." (PMID 41488138, 2025). "We also confirmed robust LEAP2 expression in insulinoma specimens using two independent antibodies, with appropriate positive and negative controls to ensure methodological reliability." (PMID 41488138, 2025). "Serum LEAP2 levels were significantly higher in patients with insulinoma than in controls (P = 0.028) and positively correlated with serum insulin levels (r = 0.408, P < 0.001) while negatively correlated with ghrelin levels (r = −0.551, P < 0.01)." (PMID 41488138, 2025). "Serum LEAP2, insulin, and ghrelin levels were measured by ELISA in patients with insulinoma and in age-, sex-, and BMI-matched controls." (PMID 41488138, 2025). "LEAP2 expression was examined in insulinoma tissue and paired adjacent pancreatic specimens by immunohistochemical staining." (PMID 41488138, 2025). "Our earlier work demonstrated that the LEAP2/ghrelin receptor is expressed in more than half of insulinomas, consistent with studies by Ekeblad and Volante." (PMID 41488138, 2025). "Using another antibody, we performed colocalization for LEAP2 and insulin via immunofluorescence staining, and we found a strong positive signal of LEAP2 within the insulinoma cells, confirming the expression of LEAP2 peptide in tumor cells." (PMID 41488138, 2025). "The co-expression of LEAP2 and its receptor suggests that LEAP2 may exert autocrine and/or paracrine effects in insulinoma, similar to ghrelin." (PMID 41488138, 2025). "The present study provides two novel findings: (i) serum LEAP2 concentrations are significantly elevated in patients with insulinoma and correlate with insulin levels, and (ii) LEAP2 peptide is extensively expressed in insulinoma tissues." (PMID 41488138, 2025). "In the present study, serum LEAP2 levels were elevated and negatively correlated with blood ghrelin levels, consistent with our previous report showing significantly reduced ghrelin in patients with insulinoma." (PMID 41488138, 2025). "Immunostaining showed that LEAP2 peptide was expressed in insulinoma tissue." (PMID 41488138, 2025). "The interactive relationship between ghrelin and LEAP2 may regulate pathophysiological status in insulinoma." (PMID 41488138, 2025). "LEAP2 expression in insulinoma tissues was not significantly correlated with clinicopathological characteristics." (PMID 41488138, 2025). "Third, the expression of LEAP2 in insulinoma tissue had not previously been identified." (PMID 41488138, 2025). "However, circulating LEAP2 levels in insulinoma and LEAP2 peptide expression in tumor tissue have not been evaluated." (PMID 41488138, 2025).
lipidosis (1 paper, 2023). "Similarly, the expression and secretory levels of the liver-expressed antimicrobial peptide LEAP2 are increased in mice with diet-induced lipidosis." (PMID 37958806, 2023).
Listeria meningitis (1 paper, 2021). Inflammation of the meninges caused by listeria monocytogenes infection, usually occurring in individuals under the age of 3 years or over the age of 50 years. "The CSF LEAP2 concentration in the patient with Listeria meningitis declined during the recovery phase." (PMID 33811478, 2021).
liver cirrhosis (1 paper, 2024). "We found that LEAP-2 was elevated in the population of drinkers, and alcohol consumption could promote the occurrence of liver cirrhosis." (PMID 38778244, 2024). "After excluding alcohol consumption factors, LEAP-2 did not affect the occurrence of liver cirrhosis (OR = 4.188, P = 0.108), but the expression level of LEAP-2 was positively correlated with the liver fibrosis index FIB-4." (PMID 38778244, 2024). "As a result, we compared the levels of LEAP-2 and the incidence of liver cirrhosis between drinkers and non-drinkers in the supplementary experiment." (PMID 38778244, 2024).
liver diseases (1 paper, 2024). "This study found that the expression level of LEAP-2 is higher in liver diseases caused by factors other than metabolism than in MAFLD, especially in ALD." (PMID 38778244, 2024). "LEAP-2 can be used to differentiate MAFLD from other liver diseases especially ALD and plays a vital role in differential diagnosis." (PMID 38778244, 2024). "We aimed to investigate the differential expression levels of CK18 M30/M65 and LEAP-2 in MAFLD, healthy controls, and other liver diseases and to evaluate their role in diagnosing MAFLD." (PMID 38778244, 2024). "In conclusion, this research has found that CK18 M30/M65 and LEAP-2 are positively correlated with the liver enzymes ALT and AST to a certain extent and can become potential biomarkers for liver diseases." (PMID 38778244, 2024).
liver fibrosis (1 paper, 2024). "Silvia Ezquerro’s study suggested that the concentration of LEAP-2 might increase with the progression of liver fibrosis." (PMID 38778244, 2024).
mood disorder (1 paper, 2022). A cognitive disorder a disturbance in which the person's mood is hypothesized to be the main underlying feature. "Local overexpression of LEAP2 in the ARC would not influence animal locomotor activity and would induce mood disorders." (PMID 36387867, 2022).
Nausea (1 paper, 2022). A sensation of unease in the stomach together with an urge to vomit. "Thus, changes in VAS ratings of hunger, prospective food consumption, or nausea could not explain the reduced food intake observed during LEAP2 infusion." (PMID 35492241, 2022).
Salmonella Infections (1 paper, 2025). Infections with bacteria of the genus SALMONELLA. "For instance, during Salmonella infection, LEAP2 expression is upregulated in embryos and gonads, suggesting its role in preventing egg contamination." (PMID 39796232, 2025). "In the case of Salmonella, it has been shown that chicken LEAP2 expression in embryos and gonads is upregulated by Salmonella infection." (PMID 39796232, 2025).
steatosis (1 paper, 2025). Increased lipid within the cytoplasm of cells. "Previous studies have demonstrated that serum levels of the peptide hormone LEAP2 are markedly elevated in patients with metabolic dysfunction-associated steatohepatitis, whereas only moderate increase was observed in simple steatosis." (PMID 40855499, 2025). "In contrast, APOB females exhibited a surprising reduction in Leap2 expression, which may contribute to their resistance to steatosis." (PMID 40855499, 2025).
virus infections (1 paper, 2021). "However, the antimicrobial effect of LEAP-2 seems to be predominantly assigned to bacterial infection given that enterocytes expressed less LEAP-2 in response to virus infections by human immunodeficiency virus (HIV) and hepatitis C virus (HCV)." (PMID 34512549, 2021).
infection (13 papers, 2014 to 2025). The state of being infected such as from the introduction of a foreign agent such as serum, vaccine, antigenic substance or organism. "During infection, LEAP2 expression is upregulated in the skin, and it disrupts the bacterial cell membrane and hydrolyzes bacterial gDNA." (PMID 39796232, 2025). "LEAP-2 also can regulate other immune signaling pathways during infection, such as the Toll-like receptor (TLR) and NOD-like receptor signaling pathways." (PMID 39860298, 2025). "In this purview, the presence of infection-associated proteins (GUSB, GZMB, LEAP2, LY6D) in estrus urine is interesting." (PMID 37104448, 2023). "In the current experiment, the expression of LEAP2 in the group challenged with C. perfringens alone was higher than that in the other infection groups with both C. perfringens and E. maxima." (PMID 37799512, 2023). "Another widely studied AMP, LEAP-2, a member of the hepcidin family, has also been found to be highly expressed in the spleen and kidney following infection with S. agalactiae." (PMID 37888440, 2023). "During peak infection (5 and 7 dpi), VH and the mRNA abundance of LEAP2, AvBD1, AvBD6, AvBD10, and Muc2 were decreased in infected chickens compared to uninfected chickens." (PMID 36867919, 2023). "Two-way ANOVA revealed that infection (P < 0.0001) had a significant impact on LEAP2 expression at 7 d PI with lower mRNA levels in EM groups regardless of feed type." (PMID 33652244, 2021). "This suggests that LEAP-2 may be involved in negatively regulating or modulating other immune responses during infection, in contrast to other antimicrobial peptides." (PMID 39860298, 2025). "Similarly, LEAP2 expression in ayu, grass carp, and mudskipper increases significantly in the liver, kidney, and spleen upon infection by V. anguillarum, A. hydrophila, and E. tarda, respectively." (PMID 40941385, 2025). "AvBD1 and LEAP2 mRNA showed decreased expression at 7 and 5 dpi, respectively, compared to 0 and 14 dpi in infected chickens, which corresponded to the time around peak infection." (PMID 36867919, 2023). "We found significant differences in Ll-LEAP2 expression levels between the control and infection groups in the skin and intestine (t-test, both P < 0.01), with a 24.7-fold up-regulation in the skin of the infection group, and a 2.6-fold down-regulation in the intestine of the infection group." (PMID 36765333, 2023). "Therefore, the downregulation of LEAP2 during E. maxima infection makes the host’s intestine more vulnerable to additional pathogen infections such as C. perfringens." (PMID 37799512, 2023). "Research about the role of LEAP2 in amphibians and reptiles is not common; however, scientists have proven LEAP2’s influence on infections and the GHSR pathway." (PMID 39796232, 2025). "At 10 d PI, neither infection nor feed had a significant impact on LEAP2 mRNA levels, but there was a trend toward lower LEAP2 levels (P = 0.0719) in +BE groups." (PMID 33652244, 2021).